MYOD1 (myogenic differentiation 1)
Diseases named in the same sentence as MYOD1 in open-access papers (continued):
Sharing a sentence is not in itself a finding about the gene and the disease.
colorectal cancer (5 papers, 2009 to 2022). A primary or metastatic malignant neoplasm that affects the colon or rectum. "Future studies should also include measurement of mRNA levels of MYOD-1 gene in normal colonic mucosa and specifically in colorectal cancers and correlation in mutated crypts." (PMID 22591756, 2012). "In this study, we have determined the frequency of methylation of the MYOD-1 gene in normal colonic mucosa and investigated to see if this is associated with established colorectal cancer risk factors primarily ageing." (PMID 22591756, 2012). "Future studies should also compare MYOD-1 with MLH-1 methylation to see how this correlates together with increasing risk of colorectal cancer." (PMID 22591756, 2012). "We have for the first time demonstrated that promoter methylation of MYOD-1 gene is a potential biomarker for detecting risk of colorectal cancer and warrants further research to establish its role into clinical practice." (PMID 22591756, 2012). "The MYOD-1 gene which is a muscle differentiation gene has been showed to be significantly methylated in colorectal cancer which, is an age related event." (PMID 22591756, 2012). "Further studies conducted to examine the role of MYOD-1 methylation as a biomarker should be case controlled against a colorectal cancer population in order to draw sensitivities and predictive values." (PMID 22591756, 2012). "PPI network analysis demonstrated that SMARCD3 could physically interacted with MAPK14 (p38α), MYOD1 and SMAD4 etc., which indicated mechanistic insights underlying SMARCD3 related colorectal cancer metastasis." (PMID 33125346, 2020). "Our study suggests that promoter gene hypermethylation of the MYOD-1 gene increases significantly with age in normal individuals and thus may offer potential as a putative biomarker for colorectal cancer." (PMID 22591756, 2012). "Notably, several genes such as ALX4, CHD5, MYOD1, NEUROG1, and RASSF5, whose methylation profile distinguishes this group of HCC patients from the other HCC patients, were previously reported to be similarly hypermethylated and associated with poor prognosis in colorectal cancer." (PMID 25093504, 2014). "A number of genes are commonly hypermethylated in colorectal cancer (CRC) including hMLH1, p16INK4a, p14ARF, RAR-β, APC, MGMT, cyclin A1, CDX1, MYOD1, COX-2 and WT-1." (PMID 19662090, 2009). "Further PPI analysis indicated that SMARCD3 might promote colorectal cancer metastasis through MAPK14, MYOD1 or SMAD4 related pathways." (PMID 33125346, 2020). "This methylation profile of multiple genes including MYOD-1 is called “CpG island methylation phenotype (CIMP)”, and it is suggested that an unknown genetic mechanism in colorectal cancer may contribute to the clustering profile of the DNA methylation of the multiple genes together." (PMID 22591756, 2012).
embryonal carcinoma (5 papers, 2013 to 2015). A non-seminomatous malignant germ cell tumor characterized by the presence of large germ cells with abundant cytoplasm resembling epithelial cells, geographic necrosis, high mitotic activity, and pseudoglandular and pseudopapillary structures formation. "Recently, it was revealed that premyogenic mesodermal genes are activated by transgenic expression of MYOD1 in undifferentiated mouse embryonal carcinoma cells." (PMID 23626698, 2013).
leiomyosarcoma (5 papers, 2018 to 2025). An uncommon, aggressive malignant smooth muscle neoplasm, usually occurring in post-menopausal women. "SCRMS may resemble fibrosarcoma or leiomyosarcoma, making desmin and myogenin and myoD1 stains important parts of the workup of infantile fibrosarcomatous lesions." (PMID 30613391, 2018).
muscular atrophy (5 papers, 2009 to 2025). "Cisplatin-induced skeletal muscle atrophy is believed to be associated with not only the activation of muscle-specific ubiquitin ligases, but also reduced levels of IGF1, MyoD1, and myogenin." (PMID 37298128, 2023).
heart failure (4 papers, 2008 to 2021). Inability of the heart to pump blood at an adequate rate to meet tissue metabolic requirements. "Our observation that Myod1 target genes Mck and Ttn, were down-regulated is suggestive that the loss of oscillation of Myod1 in the SHR is maintained in the heart failure rats." (PMID 22076133, 2011). "However, the skeletal muscle specific circadian gene Myod1 was unchanged in the heart failure animals." (PMID 22076133, 2011).
medulloblastoma (4 papers, 2018 to 2023). A malignant, invasive embryonal neoplasm arising from the cerebellum. "In the Eed-deleted and Ezh2-deleted cerebella and medulloblastomas, however, Myod1+ cells also expressed Myog and adopted a myogenic trajectory." (PMID 36635771, 2023). "We found MYOD1 mRNA in all four medulloblastoma subtypes, and Myod1 expression has previously been reported in both rare cells within the CGNP population, and in proliferative tumor cells in SHH-driven medulloblastoma in mice." (PMID 31863004, 2019). "The specific diversion of CGNPs and medulloblastoma cells into myoid fates may be related to the normal expression of the MYOD1 transcription factor during postnatal development." (PMID 36635771, 2023). "Prior studies show that WT P7 cerebella and SHH medulloblastomas contain populations of cells that express MYOD1 without inducing MYOG or activating a myogenic program." (PMID 36635771, 2023). "We analyzed transcriptomic data from human medulloblastomas to determine whether HES1 and MYOD1 are frequently expressed." (PMID 31863004, 2019).
rhabdomyoma (4 papers, 2023 to 2025). A benign mesenchymal tumor arising from skeletal or cardiac muscle. "Immunohistochemical staining was positive for MSA, Desmin, MYOD1 and Myogenin, leading to a final pathological diagnosis of adult rhabdomyoma." (PMID 39963349, 2025).
colon cancer (3 papers, 2012 to 2022). "This study proposes to look at the gene specific methylation patterns of MYOD-1 gene within the colon in normal individuals, in an attempt to understand its relationship with known risk factors of colon cancer including age, lifestyle and anthropometric measures (waist to hip ratio (WHR))." (PMID 22591756, 2012). "Taken together our findings lends support to the hypothesis that promoter methylation of MYOD-1 may be an early biomarker of CRC risk since we have shown positive association with ageing and increasing WHR, both of which are established risk factors for developing colon cancer." (PMID 22591756, 2012). "MYOD1 is a transcription factor that plays a key role in the differentiation of skeletal muscle tissue, while PPFIA4 are genes that are involved in prostate and colon cancer progression." (PMID 36672609, 2022).
glioma (3 papers, 2022 to 2025). A benign or malignant brain and spinal cord tumor that arises from glial cells (astrocytes, oligodendrocytes, ependymal cells). "The expression of HOXC6, MMP9, SHOX2 and MYOD1 was associated with hypoxia degree in glioma tissues and in recurrent cases, had a remarkable diagnostic value and a significant relationship with disease free survival in glioma patients." (PMID 36118887, 2022). "Among them, 22 genes had a degree score ≥10 and 6 genes (WT1, HOXA2, HOXC6, MMP9, SHOX2 and MYOD1) were selected to construct a signature to classify glioma patients into low- or high-risk groups." (PMID 36118887, 2022). "Interestingly, MYOD1 is known to be associated with the glioma subtype defined by different methylation profiles." (PMID 41007824, 2025). "Moreover, through performing ROC analysis, we found that HOXC6, MMP9, SHOX2 and MYOD1 had a high diagnostic value (AUC>0.7) to distinguish primary and recurrent glioma tissues." (PMID 36118887, 2022). "We first determined the expression HOXC6, MMP9, SHOX2 and MYOD1 in glioma tissues with promoter-methylation and promoter-unmethylation of MGMT." (PMID 36118887, 2022). "Higher expression levels of HOXC6, MMP9 and SHOX2, and lower expression levels of MYOD1 were observed in the glioma tissues with promoter-unmethylation of MGMT in TCGA." (PMID 36118887, 2022). "In conclusion, a risk model constructed by 6 hypoxia-driven genes (WT1, HOXA2, HOXC6, MMP9, SHOX2 and MYOD1) provide valuable clinical utility for the prognostic prediction of glioma patients." (PMID 36118887, 2022). "Heatmap analysis showed that WT1, HOXA2, HOXC6, MMP9 and SHOX2 are highly expressed in high-hypoxia glioma tissues in the TCGA, whereas MYOD1 expression is reduced." (PMID 36118887, 2022). "In the present study, through perform IHC, we found that high expression of HOXC6, MMP9 and SHOX2 and low expression of MYOD1 were observed in recurrent glioma tissues." (PMID 36118887, 2022). "Interesting, through multivariate COX regression analysis, we found that HOXC6, MMP9, SHOX2 and MYOD1 can act as independent prognostic factors for glioma." (PMID 36118887, 2022). "IHC staining of primary and recurrent glioma tissues suggested that the expression of HOXC6, MMP9, MYOD1 and SHOX2 are associated with the degree of hypoxia in gliomas as well in recurrent cases." (PMID 36118887, 2022). "Interesting, in the current study, we found that HOXC6, MMP9 and SHOX2 expression were increased in the glioma tissues with promoter unmethylation of MGMT, while MYOD1 was reduced." (PMID 36118887, 2022). "Interestingly, results from glioma tissues in the TCGA also indicated that patients with high expression levels of HOXC6, MY-OD1 and SHOX2, and low expression levels of MYOD1, had a lower disease-free survival rate." (PMID 36118887, 2022). "Similarly, we found that the expression of HOXC6, MMP9 and SHOX2 was higher in recurrent glioma tissues compared with primary glioma tissues and the expression of MYOD1 was decreased, while there were no significant changes in WT1 and HOXA2." (PMID 36118887, 2022).
ischemia (3 papers, 2015 to 2025). A hypoperfusion of the BLOOD through an organ or tissue caused by a PATHOLOGIC CONSTRICTION or obstruction of its BLOOD VESSELS, or an absence of BLOOD CIRCULATION. "In an experimental model of hindlimb ischemia, hypoxia induced a reduced protein expression of the skeletal-muscle differentiation markers (myogenic differentiation 1 (MyoD) and myogenin)." (PMID 37047427, 2023).
teratoma (3 papers, 2020 to 2021). A non-seminomatous germ cell tumor characterized by the presence of various tissues which correspond to the different germinal layers (endoderm, mesoderm, and ectoderm). "In in vivo developing Pax7−/− teratomas, however, the levels of Myod1 and Myog were significantly lower, as compared to wild type control." (PMID 34571854, 2021).
cardiomyopathy (2 papers, 2018 to 2021). A disease of the heart muscle or myocardium proper. "These heart phenotypes, despite the lack of MYOD1 involvement in the heart, demonstrate that the systemic changes induced by skeletal muscle myopathy contribute to subsequent cardiomyopathy." (PMID 29479480, 2018).
dystrophin deficiency (2 papers, 2021). "Contrary to lower percentages of PAX7- and MYOD1-positive nuclei in DMD-R3381X cultures, these results suggest that dystrophin deficiency may have an effect on translation of PAX7 and MYOD1 or as yet unidentified mechanisms, although this will require further investigation." (PMID 34516770, 2021).
lentivirus infection (2 papers, 2022 to 2023). Virus diseases caused by the Lentivirus genus. "We subsequently utilized the lentivirus infection method and infected MDBK cells with the lentivirus constructs for 48 h and then analyzed the cells for evidence of MyoD1 gene interruption." (PMID 36230312, 2022).
lung fibrosis (2 papers, 2022 to 2024). "Prior studies have identified NADPH oxidase 4 (NOX4), mouse double minute 4 homolog (MDM4), and the transcription factor myogenic differentiation 1 (MyoD) as factors that contributed to myofibroblast senescence and apoptosis resistance during persistent lung fibrosis in aged mice." (PMID 35167499, 2022).
metastatic carcinoma (2 papers, 2013 to 2024). A carcinoma which has spread from the original site of growth to another anatomic site. "Moreover, the positive expression of Desmin and MyoD1, negative expression of CK can also rule out the possibility of metastatic carcinoma." (PMID 23379991, 2013).
ovarian carcinoma (2 papers, 1997 to 2020). A malignant neoplasm originating from the surface ovarian epithelium. "We compared global levels of DNA methylation as well as methylation of a specific locus (MyoD1) in ovarian cystadenomas, ovarian tumours of low malignant potential (LMP) and ovarian carcinomas to investigate the association between changes in DNA methylation and ovarian tumour development." (PMID 9020485, 1997).
Sepsis (2 papers, 2015 to 2025). Sepsis is defined as life-threatening organ dysfunction caused by a dysregulated host response to infection. "In TA, sepsis increased expression of markers of muscle regeneration Myf5 and Myog, but not Pax7 and Myod1." (PMID 41385533, 2025).
spindle cell tumor (2 papers, 2013 to 2025). "Histologically, it is described as a highly cellular spindle cell tumor with frequent mitotic activity, staining positive for desmin, myosin, myoglobin, myogenin, and myoD1 markers." (PMID 23936713, 2013).
viral infection (2 papers, 2020 to 2021). "The tissue specific activity of PAX3 can be bypassed, as demonstrated by the induction of MYOD1 in chick neural explants in which PAX3 is provided by RCAS based viral infection for 5 days." (PMID 33175861, 2020).
acute myeloid leukemia (1 paper, 2016). Acute myeloid leukemia (AML) is a group of neoplasms arising from precursor cells committed to the myeloid cell-line differentiation. "For instance, expression of MYOD1 can predict patient survival in lung cancer patients and high expression of MEF2C is associated with poor outcome in acute myeloid leukemia (AML) patients." (PMID 27874835, 2016).
autism (1 paper, 2023). Persistent deficits in social interaction and communication and interaction as well as a markedly restricted repertoire of activity and interest as well as repetitive patterns of behavior. "The encoded protein, myogenic differentiation 1, is involved in myelin sheath formation and both common and rare variants have been associated with autism, supporting MYO1D’s role in neural development and functioning." (PMID 37794492, 2023).
Barrett esophagus (1 paper, 2017). Esophageal lesion lined with columnar metaplastic epithelium which is flat or villiform. "Myogenic differentiation 1 MYOD1 is 7 Mb to the left of the peak on chromosome 11, and was reported to have frequent hypermethylation in intestinal metaplasia tissue (Barrett’s esophagus)." (PMID 29073141, 2017).
cardiac hypertrophy (1 paper, 2016). "Down regulated of this gene suggested multiple transcriptional abnormalities including cardiac hypertrophy and influence to MYOD1 expression." (PMID 27142659, 2016).
cystadenoma (1 paper, 1997). A benign or borderline cystic epithelial neoplasm arising from the glandular epithelium. "Changes in the methylation status of the MyoD1 locus were not seen in any of ten cystadenomas analysed but were present in five of ten LMP tumours and in five of ten carcinomas (P = 0.03)." (PMID 9020485, 1997).
Esotropia (1 paper, 2021). A form of strabismus with one or both eyes turned inward ('crossed') to a relatively severe degree, usually defined as 10 diopters or more. "The expression of MYOD (1.83E-4 ± 3.43E-5) < (6.08E-3 ± 7.54E-4) was significantly lower (p < 0.05) in the paralytic esotropia versus control group." (PMID 34044792, 2021).
hyperplasia (1 paper, 2022). An abnormal increase in the number of cells in an organ or a tissue with consequent enlargement. "Hyperplasia occurs during the embryonic or early post-hatching period and is regulated by myogenic differentiation 1 (MYOD)." (PMID 36553521, 2022).
hypothyroidism (1 paper, 2022). Abnormally low levels of thyroid hormone. "RNA expression analysis revealed downregulated levels of thyroid hormone target gene Klf9 transcripts by 52.01%, indicating local hypothyroidism, in muscle tissue, while myogenic marker genes MyoD1 and Myog were not affected by hypothyroidism." (PMID 36143246, 2022).
invasive lobular carcinoma (1 paper, 2023). "MYOD1 amplification was reported to be of pronostic interest in BC, with the greatest prevalence in breast invasive lobular carcinoma as well as ROS1 amplification." (PMID 38137385, 2023).